SOX2 (SRY-box transcription factor 2)
Diseases named in the same sentence as SOX2 in open-access papers (continued):
Sharing a sentence is not in itself a finding about the gene and the disease.
endometrial cancer (continued). "In this study we tried to answer the question whether the stemness-related transcription factor gene SOX2 expression is affected by promoter methylation in endometrial cancer." (PMID 20814443, 2010). "Moreover, there was a significant correlation between SOX2 mRNA expression and hypermethylation of SOX2 in endometrial carcinomas samples (Spearman correlation coefficient = 0.470, P = .024)." (PMID 20814443, 2010). "Therefore, we decided to study the methylation and expression status of SOX2 in endometrial carcinomas." (PMID 20814443, 2010). "In addition, it has been reported that IGF2BP1 is involved in the guanylation of arginine in endometrial cancer, and the PADI2/MEK1/ERK signalling pathway-mediated dysregulation of IGF2BP1 leads to the upregulation of SOX2 expression, resulting in the malignancy of endometrial cancer cells." (PMID 36894952, 2023). "We used Western blotting to detect the downregulated expression of WTAP in endometrial cancer stem cells compared to that in Ishikawa cells, while other stem cell indicators, such as CD44, CD133, SOX2 and NANOG, were upregulated in ECSCs." (PMID 39044249, 2024). "Sox2 can act as a transcription factor to positively regulate Up-frameshift protein 1 (UPF1) expression, thereby exerting a tumor-promoting effect on endometrial cancer." (PMID 36869031, 2023). "We demonstrate that the PVT1/miR-136/Sox2/UPF1 axis plays an important role in the progression and maintenance of endometrial cancer." (PMID 36869031, 2023). "We aimed to investigate the mechanism by which PVT1 regulates the expression of Sox2 and UPF1 by targeting miR-136, thereby affecting the malignant biological behavior and cell stemness of endometrial cancer cells (ECCs) and ECSCs." (PMID 36869031, 2023). "Hypoxia was further shown to promote an endometrial cancer stem-like cell phenotype by increasing the expression of CD133, ALDH1, Oct4, Sox2 and Nanog and enhancing tumor sphere formation." (PMID 35328833, 2022). "In endometrial carcinoma, hypoxia and high level of ALKBH5 expression promote the transcription of SOX2 through demethylation, thereby increasing the stem cell-like phenotype of endometrial carcinoma." (PMID 35022030, 2022). "We found that SOX2 knockdown inhibited EGFR expression and attenuated cell proliferation in endometrial carcinoma cells." (PMID 30510261, 2018). "To examine the potential of SOX2, OCT4, NANOG, and MYC as prognostic markers in endometrial carcinoma, we correlated their expression with survival outcomes in patients." (PMID 30510261, 2018). "EGF stimulation induced SOX2 expression and promoted migration of endometrial carcinoma cells, whereas TGF-β stimulation inhibited SOX2 expression and attenuated the colony-forming ability." (PMID 30510261, 2018). "To further study how the crosstalk between SOX2 and TGF-β stimulation affect the cell fate of endometrial carcinoma, we selected a stable clone from 02/D10 cells." (PMID 30510261, 2018). "We next compared SOX2 expression in the nuclei of normal FTE of patients with benign conditions and patients with endometrial cancer (age-matched cases) and the normal FTE and corresponding ovarian tumors from patients diagnosed with HGSOC." (PMID 27492892, 2016). "After overexpressing PVT1 in endometrial cancer non-stem cells and ECSCs, the expression of Sox2 was significantly decreased as noted in the qRT-PCR analysis, while the expression of Sox2 increased after PVT1 knockdown." (PMID 36869031, 2023). "This indicates that Sox2 is a target gene of PVT1 to regulate miR-136 in endometrial cancer non-stem cells and ECSCs and has a tumor-promoting effect on endometrial cancer." (PMID 36869031, 2023). "In endometrial cancer, IGF2BP1 is a direct downstream target of peptidylarginine deiminase II (PADI2) that is required for endometrial cancer progression, and IGF2BP1 binds to the m6A sites of oncogenic SOX2 and prevents its mRNA degradation." (PMID 35541906, 2022).
endometrial cancer (continued). "In addition, we discovered that SOX2 induces EGFR in a positive feedback manner, contributing to cell cycle progression and migration of endometrial cancer cells." (PMID 30510261, 2018). "Hence, we further characterized how SOX2 crosstalks with EGFR and TGF-β signaling to affect cancer cell growth and dissemination in endometrial carcinoma." (PMID 30510261, 2018). "SOX2 mRNA level was significantly reduced in endometrial carcinoma compared with nonneoplastic endometrium (P = .045)." (PMID 20814443, 2010). "In addition, Sox2 was able to rescue the inhibitory effect of miR-136 on the malignant behavior and stem cell properties of endometrial cancer non-stem cells and ECSCs." (PMID 36869031, 2023). "In further experiments, we found that Sox2 can promote the proliferation, migration, and invasion of endometrial cancer non-stem cells and ECSCs, reduce apoptosis and cell cycle arrest, enhance cell self-renewal ability and chemotherapeutic drug resistance, and enhance stem cell marker expression." (PMID 36869031, 2023). "As a common transcription factor, Sox2 may play a role in DNA transcription in endometrial cancer non-stem cells and ECSCs." (PMID 36869031, 2023). "Both miR-136 and Sox2 were overexpressed in endometrial cancer non-stem cells and stem cells." (PMID 36869031, 2023). "In contrast, expression of SOX2 and NANOG was significantly lower in CD133+ve cells compared with CD133-ve cells, consistent with earlier findings that ALDH activity may be a better marker of endometrial cancer stem cell activity." (PMID 31083574, 2019). "Although univariate analysis showed that individual expression of SOX2, OCT4, and MYC correlated with survival, multivariate analysis revealed that SOX2 and MYC, but not OCT4, could function as independent prognostic factors in predicting survival of endometrial carcinoma." (PMID 30510261, 2018). "Through ChIP and dual-luciferase reporter assays, we found that Sox2 acts as a transcription factor for UPF1, and the overexpression of Sox2 in endometrial cancer non-stem cells and ECSCs can increase the expression of UPF1." (PMID 36869031, 2023). "All these data support the existence of the SOX2-EGFR positive feedback in some, if not all, of endometrial cancer cells." (PMID 30510261, 2018).
sarcoma (24 papers, 2013 to 2025). A usually aggressive malignant neoplasm of the soft tissue or bone. "Of note, in paediatric sarcomas, SOX2 was found to be the most associated with tumour initiation and growth, making cells with high expression of SOX2 the most fitting of the CSC phenotype." (PMID 38689429, 2024). "We observed an increase in the Nanog, Nes, Oct4, Sox2, Klf4, and Myc mRNA levels in the mice with a functional allele of Emx(+/−) and especially in the null Emx(−/−), with higher levels in the induced sarcoma compared to the control muscle tissue." (PMID 34016958, 2021). "Analysis of stemness markers showed genes NES, POUF1, and SOX2 all have a greater expression in CSC than in the parental cell lines of sarcomas, with SOX2 being significantly more expressed in the CSC cell line." (PMID 41300532, 2025). "With the expression of pluripotency factors such as OCT3/4, NANOG, KLF4 and SOX2, stemness in sarcoma is a variable condition." (PMID 37635229, 2023). "In this study, we investigated the role of stemness markers in DSRCT survival and metastasis, finding that elevated levels of SOX2 and NANOG are associated with worse survival in sarcoma patients and are elevated in metastatic DSRCT tumors." (PMID 36506091, 2022). "Lower levels of sarcoma CSC markers SOX2, NANOG, ALDH1A1, ABCB1 and ABCC1 were observed in silenced cells in 2D and in CSC-enriched cultures (single-cell and 3D/spheroid)." (PMID 35864381, 2022). "This translates to sarcoma CSC-related markers (SOX2 being the most reliable) to be upregulated in both shNT and shISG15 when cells were treated with each drug." (PMID 35864381, 2022). "Comparing the control muscle tissues and the induced sarcoma, we observed the highest expression of the stem cell genes (Oct4, Sox2, Klf4, Myc, and Nanog) and aggresivity in the sarcomas induced in the Emx1 or Emx2 KO mice." (PMID 34016958, 2021). "In subsequent studies, Sox2 turned out to be crucial in the maintenance of sarcoma CSCs; this TF is being considered as the major marker of CSCs in sarcomas." (PMID 32532153, 2020). "Stemness in sarcomas is coordinated by the expression of pluripotency factors, like SOX2, in cancer stem cells (CSC)." (PMID 32295077, 2020). "The results of this approach, together with those obtained by SOX2 knockdown and overexpression, indicate that SOX2 expression/activity is a bona fide CSC marker in sarcoma." (PMID 32295077, 2020). "In the present study, we also observed a slight increase in the number of SOX2-positive cells in the xenograft tissues, which further supports that SOX2 plays a major role in sarcoma tumorigenesis and the maintenance of CSCs." (PMID 31941033, 2020). "Overall, this study demonstrates that SOX2 is a pro-tumorigenic factor with prognostic potential in sarcoma." (PMID 32295077, 2020). "Taken together, the data from depletion and overexpression experiments suggest that SOX2 expression plays an active role in the initiation and progression of sarcomas thereby emerging as a biologically and clinically relevant feature." (PMID 32295077, 2020). "Here, we show that SOX2 depletion dramatically reduced the ability of undifferentiated pleomorphic sarcoma (UPS) cells to form tumorspheres and to initiate tumor growth." (PMID 32295077, 2020). "To further confirm the SOX2-driven tumorigenic properties in sarcoma cells, we stably overexpressed SOX2 in T-5H-O cells using lentiviral particles for the expression of SOX2 cDNA." (PMID 32295077, 2020). "Remarkably, high expression levels of Sox2 are indispensable for sarcoma cell lines to form tumors in immunodeficient mice, which suggests that the expression of this TF correlates with a CSC phenotype." (PMID 32532153, 2020).
sarcoma (continued). "We found that SOX2 is expressed in 28% of an array of 88 sarcoma patients, being UPS, synovial sarcomas and Ewing sarcomas those presenting a higher percentage of positive cases in concordance with the results of previous reports." (PMID 32295077, 2020). "Overall, our results indicate that SOX2 is a critical stemness factor able to increase the tumorigenic properties of sarcoma cells." (PMID 32295077, 2020). "Altogether, these results show that SOX2, ALDH1A1 and ALDH1A3 expression, together with their associated ALDEFLUOR activities are progressively enhanced in CSC subpopulations during sarcoma progression toward more aggressive phenotypes." (PMID 27292183, 2016). "Our data additionally demonstrates that Oct4, Nanog, Sox2, Klf4, and Myc are widely expressed at high levels across a wide variety of sarcomas and benign vascular tumors at elevated levels." (PMID 26412983, 2015). "Box and whisker plots depicting the IHC scores for Oct4, Nanog, Myc, Sox2, and Klf4 in normal vasculature, benign, borderline or malignant vascular tumors, or across a panel of various sarcomas." (PMID 26412983, 2015). "Notably, higher SOX2 expression in OS patients was related to poor overall survival, and Kaplan–Meier survival curves for sarcoma patients profiled in the GEPIA database also support this finding." (PMID 39994220, 2025). "In sarcomas, including CS, SOX2 has been found overexpressed in CSCs." (PMID 37046623, 2023). "Our findings that SOX2 is highly expressed in DSRCT, associated with worse survival in sarcoma patients, and enriched in metastatic DSRCT tumors suggest the clinical relevance of DSRCT subpopulations with high SOX2 expression and the importance of a model that enables their investigation." (PMID 36506091, 2022). "DSRCT had significantly higher expression of SOX2 than the four other sarcoma types." (PMID 36506091, 2022). "Besides, CSC and drug-resistance related genes in sarcoma such as SOX2, NANOG, ALDH1A1, ABCB1 and ABCC1 were down-regulated in 2D, as well as in CSC-enriched cultures (colony-forming and 3D/ spheroid)." (PMID 35864381, 2022). "Notably, SOX2 expression correlate with advanced-disease related parameters in patients, therefore, suggesting its possible usefulness as prognostic marker in sarcoma." (PMID 32295077, 2020). "Nuclear SOX2 expression was detected in 25 (28.4%) sarcoma samples." (PMID 32295077, 2020). "Among them, SOX2 has been shown as a common CSC-related factor in different types of sarcoma." (PMID 32295077, 2020). "However, the pro-tumorigenic features of SOX2 have been scarcely investigated in other sarcoma subtypes." (PMID 32295077, 2020). "In addition, we show that SOX2 overexpression, explored for the first time in sarcoma, also support the prominent role of SOX2 in sarcomagenesis." (PMID 32295077, 2020). "In addition, the level of SOX2 expression in a panel of primary sarcoma cell lines have been positively correlated with the ability to grow tumors in immunodeficient mice." (PMID 32295077, 2020). "Additionally, it has been highlighted that all the sarcoma cell lines with high ALDH activity overexpress Sox2." (PMID 32532153, 2020). "The elevated IHC scores observed for malignant and borderline vascular tumors correlated to the results obtained in a diverse panel of malignant sarcoma cells, revealing immunoreactivity for Oct4, Nanog, and Sox2 in 100 % of various sarcoma tissues and 72 % for Myc and Kfl4." (PMID 26412983, 2015). "This hypothesis is further bolstered by the high expression of SOX2 in DSRCT relative to other fusion sarcomas and the finding that extraperitoneal metastatic DSRCT samples express higher levels of stemness markers (SOX2 and NANOG) than intraperitoneal DSRCT tumors." (PMID 38177125, 2024). "The system allows for isolating SOX2/OCT4 positive cells and thus analyzing the tumor-promoting CSC in sarcoma." (PMID 37046623, 2023).
sarcoma (continued). "NANOG is important for CSC maintenance, as it regulates the expression of other stem cell markers OCT4, SOX2, KLF4, and promotes sarcoma CSC features such as spheroid formation, anchorage-independent growth, migration and invasion." (PMID 35145908, 2021). "Our work showed that EMX1/EMX2 act as tumor suppressors in sarcomas by repressing the activity of stem cell regulatory genes (OCT4, SOX2, KLF4, MYC, NANOG, NES, and PROM1)." (PMID 34016958, 2021). "In summary, our work showed that EMX1 and EMX2 act as tumor suppressors by suppressing the activity of stem cell regulatory genes (OCT4, KLF4, MYC, SOX2, NANOG, NES, and PROM1) in sarcoma." (PMID 34016958, 2021). "SOX2 and OCT4 expression was analyzed by immunohistochemistry in a collection of tissue microarrays, including samples from 10 types of sarcomas." (PMID 32295077, 2020). "The stemness state in sarcomas is orchestrated by the expression of pluripotency factors such as OCT3/4, NANOG, KLF4, and SOX2." (PMID 32295077, 2020). "FOXM1 stimulates transcription of pluripotency related genes including SOX2, KLF4, OCT4, and NANOG many of which are important in sarcoma, a disorder of mesenchymal stem cell/ partially committed progenitor cells." (PMID 27074562, 2016). "Survival analysis revealed that higher expression of SOX2, NANOG, and MYC but not OCT4 (POU5F1) or KLF4 is associated with significantly reduced survival in sarcoma patients." (PMID 36506091, 2022). "Moreover, the transcriptional activity of SOX2 and/or OCT4, measured using the SORE6 reporter, is a bona fide CSC marker in sarcoma and constitutes an excellent approach for testing the effectiveness of anti-tumor treatments to target CSCs." (PMID 32295077, 2020). "These experiments suggest that high SOX2/OCT4 transcriptional activity, measured by SORE6 activity, could be used as a surrogate marker for CSCs in sarcomas." (PMID 32295077, 2020). "We aimed to investigate whether the expression of pluripotency factors such as SOX2 and OCT4 in sarcoma patients is clinically relevant." (PMID 32295077, 2020). "Recently, the presence of increased ALDH1 activity allowed the identification of a subpopulation of human sarcoma cell lines with stem cell properties, including high level of expression of stem cell genes such as NANOG, OCT3/4, STAT3 and SOX2, and resistance to chemotherapy." (PMID 23734203, 2013). "Although the first studies suggested prominin-1 (CD133) or nestin as rhabdomyosarcoma CSC markers, our recent study showed that, regardless of these proteins, only sarcoma cell lines that express high levels of the transcription factor SOX2 form tumors in immunodeficient NOD/SCID gamma (NSG) mice." (PMID 31941033, 2020). "In summary, we found that SOX2, but not OCT4, correlated with advanced tumor stages, aggressive phenotypes and poor prognosis in sarcoma patients." (PMID 32295077, 2020). "According to these data SOX2, rather than OCT4, might primarily play an active role in the initiation and progression of sarcomas." (PMID 32295077, 2020).